CXCL13 (C-X-C motif chemokine ligand 13)
Diseases named in the same sentence as CXCL13 in open-access papers (continued):
Sharing a sentence is not in itself a finding about the gene and the disease.
neurosyphilis (continued). "Does the CXCL13 concentration relate to the progression of neurosyphilis?" (PMID 27376011, 2016). "In the search for biomarkers of neurosyphilis, we investigated the chemokine profile in CSF of neurosyphilis patients and found that the concentrations of CXCL13, CXCL10 and CXCL8 were selectively elevated in neurosyphilis patients and correlated with CSF protein concentration and CSF-VDRL titer." (PMID 27650493, 2016). "The relationship between CXCL13 and neurosyphilis still needs further study." (PMID 27376011, 2016). "Therefore, serum CXCL13 levels can’ t be used to support the diagnosis of neurosyphilis in HIV-negative patients." (PMID 27376011, 2016). "Thus, the CSF/serum ratio of CXCL13 in neurosyphilis patients (median 48.35, ranged from 0.09 to 2854.3) was greatly higher than that in non-neurosyphilis patients (median 0.32, ranged from 0.02 to 13.6, p = 0.000)." (PMID 27650493, 2016). "However, the difference in the mean baseline CXCL13 levels was statistically significant for both neurosyphilis and LNB compared to MS (p < 0.05, p < 0.001, respectively)." (PMID 25975424, 2015). "Whether a general cut-off for diagnosing LNB would be reasonable remains doubtful in the context of our finding that the CSF of patients with neurosyphilis can also show high levels of CXCL13." (PMID 25975424, 2015). "CXCL13 levels might be part of the inflammatory response to infection of the CNS with T. pallidum and may serve as a marker of disease activity in neurosyphilis." (PMID 25975424, 2015). "The single patient with neurosyphilis had a CXCL13 level of 37,000 pg/ml." (PMID 24920219, 2014). "Neurosyphilis is known to elevate the level of CXCL13 in the CSF." (PMID 24920219, 2014). "CXCL13 in the CSF sample of the single neurosyphilis patient was 37,000 pg/ml." (PMID 24920219, 2014). "CXCL13 is secreted by secondary lymphoid tissue, dendritic cells and lymph nodes and is involved in the regulation and migration of B-cells, correlating well with the concentrations of intrathecal B- and T-cells,and has been investigated as a biomarker for confirmed and asymptomatic neurosyphilis." (PMID 38983560, 2022). "Thus, it is suggested that CSF CXCL13 concentration may be helpful for the diagnosis and therapeutic evaluation of neurosyphilis." (PMID 33336020, 2020). "The CSF CXCL13 level in neurosyphilis patients (median 1905.7 pg/ml, ranged from 15.6 to 57526.1 pg/ml) was the most significantly elevated chemokine in comparison with that in non-neurosyphilis patients (median 15.6 pg/ml, ranged from 15.6 to 4564.39 pg/ml, p = 0.000)." (PMID 27650493, 2016). "This study systematically assessed the predictive accuracy of single and combined indicators—CXCL13, WBC, and Hs-CRP—for the rehabilitation outcomes of stroke patients with neurosyphilis by evaluating the AUC." (PMID 40070668, 2025). "This study evaluates the predictive value and clinical significance of CXCL13, WBC, and Hs-CRP levels in neurosyphilis patients undergoing HBO and TUS-NMES therapy." (PMID 40070668, 2025). "The receiver operating characteristic (ROC) curve analysis revealed differing predictive capabilities for the biomarkers CXCL13, WBC, and Hs-CRP in assessing the rehabilitation outcomes of stroke patients with neurosyphilis." (PMID 40070668, 2025). "CXCL13, CXCL10 and CXCL8 showed AH levels equivalent to previously reported levels in the CSF of patients with neurosyphilis and can potentially be an adjunct in the diagnosis and management of ocular syphilis." (PMID 38983560, 2022). "They found that CXCL13, CXCL10 and CXCL8 levels were significantly increased in the neurosyphilis group." (PMID 38983560, 2022). "The concentrations of CXCL13, CXCL10, and CXCL8 were increased in the CSF of neurosyphilis patients, which was related to the CSF protein concentration and the CSF-VDRL titer." (PMID 36452956, 2022).
neurosyphilis (continued). "Recent studies showed a significantly elevated levels of IL-8, CC chemokine ligand 20 (CCL-20) in serum, elevated levels of CXCL13, interferon(IFN)-γ in CSF, and elevated levels of IL-6, IL-10, IL-17 in both serum and CSF of neurosyphilis patients." (PMID 36203756, 2022). "The levels of CXCL13, CXCL10 and CXCL8 in the AH of patients with neurosyphilis are similar to previously reported levels in the CSF of patients with neurosyphilis and can potentially be an adjunct in the diagnosis of ocular syphilis." (PMID 38983560, 2022). "The sensitivity/specificity of CXCL13, CXCL10, and CXCL8 in the diagnosis of neurosyphilis were 85.4/89.1%, 79/90.1%, and 79.6/91.1%, respectively." (PMID 36452956, 2022). "Detection of CSF CXCL13 concentration is helpful for the diagnosis and therapeutic evaluation of HIV-negative latent syphilis patients with treatment failure and neurosyphilis." (PMID 33336020, 2020). "Several recent studies have shown that CSF CXCL13 concentration is elevated in both HIV‐positive and HIV‐negative patients with neurosyphilis." (PMID 32419252, 2020). "The AUCs of CSF CXCL13, CXCL8, and CXCL10 were all approximately 0.9 in a previous study, indicating that these chemokines are not only potential biomarkers as complementary diagnostic tools for neurosyphilis but may also be useful for monitoring therapeutic effects." (PMID 32419252, 2020). "CXCL13 and CXCL8/IL-8 have been already studied (individually and in combination with IL-12p40 or CXCL10) in the context of MS and neurosyphilis." (PMID 31356620, 2019). "Given the measurements were correlated with the disease activity, we therefore investigated the correlation between CSF CXCL13, CXCL10 and CXCL8 levels and these measurements in neurosyphilis patients." (PMID 27650493, 2016). "The corresponding sensitivities/specificities of CSF CXCL13, CXCL8,CXCL10 and the CSF/serum ratio of CXCL13, CXCL8,CXCL10 in diagnosis of neurosyphilis were 85.4%/89.1%, 79%/90.1% and 79.6%/91.1%, 86.6%/99%, 79%/73.3% and 86%/92.1%, respectively." (PMID 27650493, 2016). "The area under the ROC curve (AUC) of CSF CXCL13, CXCL8,CXCL10 and the CSF/serum ratio of CXCL13, CXCL8,CXCL10 in the diagnosis of neurosyphilis were 0.940, 0.899, 0.915, 0.963, 0.846 and 0.926, respectively." (PMID 27650493, 2016). "Elevated levels of CXCL13 were also reported for CNS lymphoma, HIV infection, cryptococcosis, and neurosyphilis." (PMID 25975424, 2015). "CXCL13, a chemokine ligand, is notably elevated in the CSF of neurosyphilis patients compared to those without the condition." (PMID 40070668, 2025). "CXCL13/CXCR5 mediated the aggregation of B cells, which directed the aberrant humoral immune responses via the formation of EGCs, suggesting neurological damage in neurosyphilis." (PMID 36419997, 2022). "If a CSF CXCL13 level of more than 250 pg/mL was added as an additional criterion to the current UTD guidelines for diagnosing neurosyphilis, another four patients would have been classified as having neurosyphilis." (PMID 38983560, 2022). "They used a positive CSF rapid plasma reagin (RPR) test, and not the clinical symptoms, to diagnose neurosyphilis and found a CXCL13 cut-off value of 76.3 pg/ml to be 50% sensitive and 90% specific for diagnosing neurosyphilis." (PMID 38983560, 2022). "measured the levels of CXCL13 in the CSF of patients with neurosyphilis and uncomplicated syphilis who tested positive or negative for HIV." (PMID 38983560, 2022). "The addition of CXCL13 measurements in the routine testing of our patients would, therefore, have made a difference in the classification of our patients to have neurosyphilis or not." (PMID 38983560, 2022). "The two non-LNB patients who had positive CSF CXCL13 results in both assays were the ones diagnosed with neurosyphilis and tuberculous meningitis." (PMID 34132584, 2021). "The determination of CXCL13 in the CSF in neurosyphilis is not recommended due to the lack of large studies." (PMID 33225223, 2020).
neurosyphilis (continued). "Currently, the determination of CXCL13 in the CSF in neurosyphilis is not recommended due to the lack of large studies." (PMID 33225223, 2020). "Increased CXCL13 levels do not appear to be present in all patients with neurosyphilis, however, and different CSF levels of CXCL13 in patients with symptomatic neurosyphilis and asymptomatic neurosyphilis have been reported." (PMID 33225223, 2020). "Interestingly, before treatment began, CXCL13 showed a correlation with a serum rapid plasma reagin (RPR) test, which measures the concentration of antibodies typically produced in neurosyphilis." (PMID 32331231, 2020). "Our results suggest that the elevated concentrations of CXCL13, CXCL8, and CXCL10 or their increasing CSF/serum ratios may be potential biomarkers of neurosyphilis, particularly for asymptomatic neurosyphilis." (PMID 27650493, 2016). "The CSF CXCL13 and QCXCL13 could serve as valuable biomarkers for differentiating neurosyphilis from non-neurosyphilis/syphilis in HIV-negative patients." (PMID 27376011, 2016). "Given the marked elevation of CSF CXCL13, CXCL10 and CXCL8 as well as CSF/serum ratio of these chemokines in neurosyphilis patients, we further evaluated these chemokines as biomarkers in neurosyphilis diagnosis using the receiver operating characteristic (ROC) curve analysis." (PMID 27650493, 2016). "ROC analysis revealed that the CSF CXCL13 levels were robust in discriminating patients with neurosyphilis and non-neurosyphilis/syphilis, with an AUC value of 0.831 (95 % CI 0.724–0.938, P = 0.000)." (PMID 27376011, 2016). "In our study, CSF and serum CXCL13 concentrations were detected among 40 neurosyphilis patients, 31 syphilis/non-neurosyphilis patients, 26 non-syphilis/other central nervous system diseases patients." (PMID 27376011, 2016). "The serum CXCL13 level was significantly higher in the neurosyphilis and syphilis/non-neurosyphilis groups than in the healthy volunteers (χ2 = 48.491, P < 0.001; χ2 = 17.170, P < 0.001)." (PMID 27376011, 2016). "The results showed that the QCXCL13 in neurosyphilis patients was significantly higher than in syphilis/non-neurosyphilis patients, suggesting that intrathecal synthesis of CXCL13 did occur in HIV-negative neurosyphilis patients." (PMID 27376011, 2016). "In recent years, CSF CXCL13 concentrations have been suggested as a marker for the diagnosis of neurosyphilis in HIV-infected patients because they are independent of CSF pleocytosis and the markers of HIV." (PMID 27376011, 2016). "The results showed that serum CXCL13 concentrations had no value to differentiate between neurosyphilis and other neurologic viral and cryptococcal infection diseases or other noninflammatory neurological disorders." (PMID 27376011, 2016). "But there was no different in serum CXCL13 level either between neurosyphilis group and syphilis group, or neurosyphilis group and non-neurosyphilis group." (PMID 27376011, 2016). "Furthermore, we explored the differences in the concentrations of CXCL13 in the serum and CSF and the QCXCL13 among patients with different types of neurosyphilis." (PMID 27376011, 2016). "For asymptomatic neurosyphilis, the AUC of Model 2 was not statistically different from that of the ratio of CSF/serum CXCL13 (p = 0.6634), but it was higher than that of CSF VDRL (p = 0.0412)." (PMID 27650493, 2016). "Thus, we assessed the efficacy of combined CSF CXCL13, CXCL10 and CXCL8 (Model 1) and combined the ratio of CSF/serum CXCL13, CXCL10 and CXCL8 (Model 2) as biomarkers for diagnosis of neurosyphilis." (PMID 27650493, 2016). "The median baseline CXCL13 levels in the CSF samples were 972 pg/mL (IQR 213–6,870, range 134–7,140) for patients with neurosyphilis, 8,000 pg/mL (IQR 4,170–20,747; range 3,247–29,110) for patients with LNB, and 7.8 pg/mL (IQR 7.8–20.6; range 7.8–59.4) for patients with MS." (PMID 25975424, 2015).
neurosyphilis (continued). "There was a non-significant trend toward higher baseline values of CXCL13 in patients with LNB compared to neurosyphilis." (PMID 25975424, 2015). "This is the first controlled study reporting on CXCL13 levels in CSF from patients diagnosed with neurosyphilis but without confounding co-infections at the time of the first diagnosis and during the course of treatment." (PMID 25975424, 2015). "Further, the newly proposed biomarker CXCL13 for LNB, which increases in CSF even before IAP detection and rapidly decreases during antibiotic treatment, is also not increased in LNB without IAP detection and can also be detected in other disorders (e.g., neurosyphilis and CNS lymphoma)." (PMID 39736882, 2025). "The following statistically significant findings became apparent when we compared the group diagnosed as having neurosyphilis with the group diagnosed as not having neurosyphilis: The mean CXCL13 concentration was higher in the AH than the serum of participants with neurosyphilis (p=0.02)." (PMID 38983560, 2022). "The use of CXCL13 as an adjunctive test for patients who tested HIV-negative has been shown to be valuable, with significantly elevated levels of CXCL13 in the CSF compared with the serum, indicating intrathecal CXCL13 production in patients with neurosyphilis." (PMID 38983560, 2022). "The AUC of Model 2 was not statistically different from that of the ratio of CSF/serum CXCL13 and CSF VDRL (p = 0.3968, p = 0.1386, respectively), but it was higher than that of the ratio of CSF/serum CXCL8 and CXCL10 (p < 0.0001, p = 0.007, respectively) for all neurosyphilis." (PMID 27650493, 2016). "Therefore, CSF CXCL13 and QCXCL13 may be useful as markers for the diagnosis of neurosyphilis in HIV-negative patients." (PMID 27376011, 2016). "In conclusion, when infection of T. pallidum occurs, CSF CXCL13 levels and QCXCL13 may be potential markers for the diagnosis of neurosyphilis, as demonstrated by the elevated CSF CXCL13 levels in patients with suspected neurosyphilis." (PMID 27376011, 2016). "We found that CSF CXCL13 could also serve as a valuable supplementary biomarker for differentiating neurosyphilis from non-neurosyphilis/syphilis with HIV-negative patients." (PMID 27376011, 2016). "However, the serum CXCL13 level was significantly higher in non-neurosyphilis patients than that in neurosyphilis patients (p = 0.000)." (PMID 27650493, 2016). "The CSF concentrations of CXCL13 were remarkably increased in patients with neurosyphilis compared to patients with syphilis/non-neurosyphilis (χ2 = 21.802, P < 0.001) and patients with non-syphilis/non central nervous system (CNS) infection group (χ2 = 9.340, P = 0.009)." (PMID 27376011, 2016). "The results showed that serum CXCL-13 could not differentiate the neurosyphilis from other neurologic viral and cryptococcal infection diseases." (PMID 27376011, 2016). "In addition, studies have shown that the levels of CSF protein and white blood cell count are positively correlated with the inflammatory markers CXCL13, IL-6, and IL-10, which suggests that patients with atypical neurosyphilis may not have a significant or active inflammatory response." (PMID 41376790, 2025). "We hope to further evaluate the specificity of CXCL13, CXCL10 and CXCL8 in the diagnosis of neurosyphilis, so that NS can be independently diagnosed without interference from other factors." (PMID 41221293, 2025). "The HIV-positive group had higher levels of CXCL13, CXCL10 and CXCL8, but this was not statistically influenced by the neurosyphilis status in these patients with ocular syphilis." (PMID 38983560, 2022). "The mean concentrations of CXCL13 in the AH of participants infected with HIV were also higher than the serum concentrations in participants both with and without neurosyphilis (p<0.01) and the CSF concentrations of participants not infected with HIV (p=0.01)." (PMID 38983560, 2022).
neurosyphilis (continued). "Our findings also show that the analysis of the chemokines CXCL13, CXCL10 and CXCL8 in the CSF can indicate the occurrence of neuroinflammation in patients who do not meet the criteria for being diagnosed with neurosyphilis." (PMID 38983560, 2022). "We found that the levels of CXCL13, CCL24, CXCL8, CXCL10, and CXCL7 were significantly higher in the CSF of those with than those without neurosyphilis." (PMID 32419252, 2020). "It has been demonstrated that patients with neurosyphilis and HIV co-infection have higher serum concentrations of CXCL13 than HIV-infected patients with syphilis, but without neurological symptoms." (PMID 32331231, 2020). "The levels of CCL24 (P = .0185), CXCL7 (P < .0001), CXCL13 (P < .0001), CXCL10 (P < .0001), and CXCL8 (P < .0001) in the CSF of neurosyphilis patients were higher than those in the CSF of patients without neurosyphilis." (PMID 32419252, 2020). "Antibody array analysis showed that the CSF levels of CCL24 (P = .0185), CXCL7 (P < .0001), CXCL13 (P < .0001), CXCL10 (P < .0001), and CXCL8 (P < .0001) were significantly higher in patients with than without neurosyphilis." (PMID 32419252, 2020). "But it was not statistically different compared with that of CSF CXCL13 and CSF VDRL for all neurosyphilis (p = 0.1167, p = 0.3237, respectively) and for asymptomatic neurosyphilis (p = 0.6399, p = 0.8994, respectively)." (PMID 27650493, 2016). "CSF CXCL13 levels and the QCXCL13 are novel important promising biomarkers in differentiating neurosyphilis patients from non-neurosyphilis/syphilis patients without HIV infection." (PMID 27376011, 2016). "We found that the CSF CXCL13 concentrations and CXCL13 quotient (QCXCL13) were significantly increased in neurosyphilis patients compared to syphilis/non-neurosyphilis (χ2 = 21.802, P < 0.001) and non-syphilis patients (χ2 = 7.677, P = 0.002)." (PMID 27376011, 2016). "Also, the AH/serum ratio of CXCL13 and CXCL10, as well as the CSF/serum ratio of CXCL10, was much higher in patients with neurosyphilis than without." (PMID 38983560, 2022). "ROC curve analyses revealed that CSF CXCL13 concentrations and QCXCL13 could serve as valuable biomarkers for differentiating neurosyphilis from non-neurosyphilis/syphilis." (PMID 27376011, 2016). "The concentrations of CXCL13 in the serum (χ2 = 72.115, P < 0.001) and CSF (χ2 = 22.653, P < 0.001) and QCXCL13 (χ2 = 15.110, P = 0.001) were different among the neurosyphilis group, the syphilis/non-neurosyphilis group, the non-syphilis group and the healthy volunteers." (PMID 27376011, 2016). "Consistent with the antibody array data, the levels of CSF CXCL13, CXCL8 and CXCL10 were 45.9 (ranged from 0.09 to 341.42), 4.3 (ranged from 0.43 to 31.96), 7.2 (ranged from 0.37 to 67.16) fold higher in neurosyphilis patients than those in non-neurosyphilis patients, respectively." (PMID 27650493, 2016). "In patients with ocular syphilis and neurosyphilis the AH/serum ratio for CXCL13, CXCL10 and CXCL8 was 3.78, 89.72 and 24.92 respectively while in patients with ocular syphilis without neurosyphilis the AH/serum ratio for CXCL13, CXCL10 and CXCL8 was 2.82, 76.89 and 14.04 respectively." (PMID 38983560, 2022).